VCAM1 (vascular cell adhesion molecule 1)
Diseases named in the same sentence as VCAM1 in open-access papers (continued):
Sharing a sentence is not in itself a finding about the gene and the disease.
Immunodeficiency (4 papers, 2020 to 2024). Failure of the immune system to protect the body adequately from infection, due to the absence or insufficiency of some component process or substance. "Elevated VCAM-1 in the serum has been associated with immune system disorders." (PMID 39262670, 2024). "It has also been shown that PHC2 can bind to the Vcam1 locus and act to reduce systemic immunodeficiency." (PMID 37138862, 2023). "Although it is possible that immunodeficiency in the mice might have affected the allograft study, results observed in PKF mice treated with anti-VCAM-1 antibody suggested that immunocompetent mice have similar responses in terms of sVCAM-1 mediated resistance to gemcitabine." (PMID 33273652, 2020).
intracerebral hemorrhage (4 papers, 2019 to 2023). A cerebrovascular disorder characterized by bleeding into one or both cerebral hemispheres including the basal ganglia and the cerebral cortex. "miR-126-3p attenuates intracerebral hemorrhage-induced blood-brain barrier disruption, which is associated with down-regulated expression of VCAM-1 in hemorrhagic area." (PMID 31474826, 2019). "Another study reported that miR126 was lower in patients with intracerebral hemorrhage and that using miR126 mimics to downregulate VCAM-1 in the rat model of intracerebral hemorrhage." (PMID 37917636, 2023). "Another miRNA, miR-126, was shown to attenuate intracerebral hemorrhage-induced leukocyte adhesion and BBB disruption by targeting vascular cell adhesion molecule-1 (VCAM-1), a classic inflammation marker critical for leukocyte adhesion to blood vessels." (PMID 34178963, 2021).
kidney injury (4 papers, 2020 to 2025). Trauma to the kidney. "Future experiments with the combination of E-selectin, P-selectin, and VCAM-1 blockers given simultaneously might attenuate the manifestation of adenine-diet-induced kidney injury." (PMID 39861730, 2025). "Furthermore, consistent with a previous finding in the mouse model with acute kidney injury, overexpression of Klf4 also inhibited adhesion cytokines, including VCAM‐1 and ICAM‐1 (P < .05)." (PMID 31800161, 2020).
lymphoma (4 papers, 2009 to 2019). A malignant (clonal) proliferation of B- lymphocytes or T- lymphocytes which involves the lymph nodes, bone marrow and/or extranodal sites. "In human T-lymphoblastic lymphoma, VCAM-1 is expressed not only in lymphoma cells, but also on both the apical and the basolateral surfaces of endothelial cells, consequently activating the sequential transmigration and intravasation of lymphoma cells." (PMID 19773759, 2009). "The expression of integrin α4ß1 by lymphoma cells may be partially responsive for metastasis of lymphomas to the bone marrow where marrow stomal cells express VCAM-1." (PMID 30657059, 2019).
migraines (4 papers, 2022 to 2025). "Additionally, higher expression of VCAM1 was found to be associated with lower migraine severity (Spearman’s correlation coefficient = −0.559; p = 0.010) and headache impact test-6 scores (Spearman’s correlation coefficient = −0.596; p = 0.007)." (PMID 38338971, 2024). "In the case of the present study, the treatment of women suffering episodic migraines with ALA significantly decreased serum VCAM-1 concentration." (PMID 34997178, 2022). "The results of the present study showed that 3 months of ALA supplementation in women with episodic migraines led to a significant reduction in serum lactate and VCAM-1 levels." (PMID 34997178, 2022). "None of the previous studies designed to investigate the effect of ALA intake on migraine had determined VCAM-1 levels." (PMID 34997178, 2022). "Additionally, expression of VCAM1 negatively correlated with migraine-related disability (headache impact test-6 scores), as well as migraine severity in the follicular phase." (PMID 38338971, 2024). "Thus, the existing study was designed to assess the effects of alpha-lipoic acid supplementation on lactate serum levels, nitric oxide, VCAM-1, and clinical symptoms in women with episodic migraines." (PMID 34997178, 2022). "We also found associations between the expression of CALCA, EDN1, IL6, NOS3, VCAM1, and VEGF and measures of cerebrovascular function and migraine-related disability when menstrual phase (i.e., follicular, mid-cycle, or luteal) was accounted for." (PMID 38338971, 2024). "The current study was performed to evaluate the effects of alpha-lipoic acid (ALA) supplementation on lactate, nitric oxide (NO), vascular cell adhesion molecule-1 (VCAM-1) levels, and clinical symptoms in women with episodic migraines." (PMID 34997178, 2022). "In patients experiencing migraines, vascular disorder leads to endothelial activation and increased generation of factors such as inflammatory cytokines, intercellular adhesion molecule (ICAM), and vascular cell adhesion molecule-1 (VCAM)." (PMID 35190593, 2022).
neuroblastoma (4 papers, 2015 to 2024). Neuroblastoma (NB) is the most common solid, extracranial childhood tumor. "The ligation of RAGE by CML was shown to upregulate the RAGE expression in human neuroblastoma cell line SH-SY5Y as well as enhance the expression of vascular cell adhesion molecule-1 (VCAM-1) on endothelial cells." (PMID 28777346, 2017). "We show that α4 expression in human and murine neuroblastoma cell lines selectively enhances in vitro interaction with the alternatively spliced connecting segment 1 of fibronectin, as well as vascular cell adhesion molecule-1 and increases migration." (PMID 25973900, 2015). "Moreover, RA has been reported to significantly increase VCAM1 antigen expression in human neuroblastoma cells." (PMID 38827116, 2024).
neuropathy (4 papers, 2021 to 2025). A disorder affecting the nervous system that manifests with pain, tingling, numbness, and/or muscle weakness. "Patients received autologous DC administration, with their Toronto Clinical Neuropathy Score (TCNS), Transforming Growth Factor-β (TGF-β), and Vascular Cell Adhesion Molecule-1 (VCAM-1) levels measured before and at four weeks after treatment." (PMID 39727989, 2024). "Although the changes in TGF-β and VCAM-1 levels showed an improvement trend in the “improved” neuropathy group, these results were not statistically significant enough to be considered a definite effect of the intervention." (PMID 39727989, 2024). "In contrast, in the “improved” neuropathy group, there was an increase in VCAM-1 levels of 41.25 ng/mL, but this increase was also not significant (p > 0.05)." (PMID 39727989, 2024). "In the “no-change” in neuropathy group, VCAM-1 levels decreased by 6.25 ng/mL, but this decrease was not statistically significant (p > 0.05)." (PMID 39727989, 2024). "Moreover, the factors associated with DSP signs and symptoms differed in PWH (Factor 2, VCAM-1, and sTNFRII) and PWoH (Factor 4, MMP-2), suggesting that the biological determinants of neuropathy signs and symptoms differ between people with and without HIV." (PMID 38673830, 2024).
osteoporosis (4 papers, 2018 to 2026). A condition of reduced bone mass, with decreased cortical thickness and a decrease in the number and size of the trabeculae of cancellous bone (but normal chemical composition), resulting in increased fracture incidence. "The current study has investigated the relationship between miR-142-5p and VCAM-1 in the osteoporosis setting." (PMID 29789783, 2018). "Collectively, these data indicated the important role of miR-142-5p in osteoporosis development involving targeting VCAM-1 and inhibiting BMMSC migration." (PMID 29789783, 2018). "miR-142-5p has been proven in the current study to be the most significantly induced miRNA in BMMSCs and bind to 3′UTR of VCAM-1 to inhibit VCAM-1 expression in OVX-induced osteoporosis in rats." (PMID 29789783, 2018). "Na-DHA may increase osteoporosis risk by upregulating LCMT1, downregulating ARHGEF11 and VCAM1, and disrupting lipid metabolism and the balance between osteogenesis and adipogenesis, ultimately disrupting bone metabolic homeostasis." (PMID 41804343, 2026). "This MiRNA also reduces MSCs migration through VCAM1, contributing to osteoporosis." (PMID 36831188, 2023). "This study has also shown that downregulated VCAM-1 inhibits migration of BMMSCs in osteoporosis." (PMID 29789783, 2018). "However, potential functions of miR-142-5p and VCAM-1 in osteoporosis have been hardly reported previously." (PMID 29789783, 2018).
pancreatic ductal adenocarcinoma (4 papers, 2018 to 2025). An infiltrating adenocarcinoma that arises from the epithelial cells of the pancreas. "VCAM-1 was found to be highly expressed in human pancreatic ductal adenocarcinoma (PDAC) tissues and cell lines, and is associated with disease progression and predicts clinical outcome in PDAC patients." (PMID 29670110, 2018). "In pancreatic ductal adenocarcinoma, restoring VCAM-1 expression enhances T-cell infiltration, inhibits tumor growth, and is associated with longer survival." (PMID 41583457, 2025). "NF-κB activated by CCL18 is equally responsible for the increase in the expression of the vascular cell adhesion molecule-1 (VCAM-1) on pancreatic ductal adenocarcinoma cells." (PMID 33114763, 2020).
progressive multifocal leukoencephalopathy (4 papers, 2017 to 2023). Progressive multifocal leukoencephalopathy (PML) is a neurological disorder that damages the myelin that covers and protects nerves in the white matter of the brain. "However, due to the ubiquitous expression of VCAM-1, systemic blocking of the VCAM-1 homing cascade was associated with severe adverse events like progressive multifocal leukoencephalopathy (PML), underscoring the need for gut-selective targeting of T cell trafficking." (PMID 34017333, 2021). "Soon after approval of natalizumab for CD, a report of progressive multifocal leukoencephalopathy (PML) was published, a severe infectious side effect deemed to arise from concurrent inhibition of α4β1-dependent homing via vascular cell adhesion molecule (VCAM)-1 to the central nervous system." (PMID 28804488, 2017).
renal dysfunction (4 papers, 2013 to 2025). "•VCAM-1 levels were correlated with kidney biomarkers, indicating potential endothelial damage alongside renal dysfunction." (PMID 40525140, 2025). "The intense interaction between urinary NGAL and the level of VCAM-1, Ang-1, and Ang-2 before antivenom administration in linear mixed models highlights the importance of repairing the endothelial to overcome tubular and functional renal dysfunction." (PMID 40525140, 2025). "Importantly, a significant correlation was found between VCAM-1 and the Horowitz index (r = 0.3115), PCT (r = 0.3664), IL-6 (r = 0.4599) and E-selectin (r = 0.3643), while an inverse association was analyzed with renal dysfunction evaluated by GFR (r = −0.5076)." (PMID 38276214, 2024). "Notably, in cirrhotic ascitic rats from our study, chronic pioglitazone pre-treatment attenuated LPS-induced TNFα/NFκB-mediated acute on chronic renal dysfunction by suppressing renal IL-6, ICAM-1 and VCAM-1." (PMID 34831270, 2021).
schizophrenia (4 papers, 2021 to 2025). A major psychotic disorder characterized by abnormalities in the perception or expression of reality. "VCAM-1 participates in autoimmune disorders; it has been linked to cardiovascular diseases, stroke, cancer, and psychiatric disorders such as schizophrenia and bipolar disorder." (PMID 41225971, 2025). "Changes in vascular endothelial growth factor (VEGF), intercellular adhesion molecule-1 (ICAM-1), and vascular cell adhesion molecule-1 (VCAM-1) levels have also been observed in schizophrenia patients." (PMID 39940642, 2025). "Elevated levels of soluble or membrane-bound ICAM-1 and VCAM-1 levels have been reported in the CSF or brains of individuals with schizophrenia, unipolar or bipolar depression." (PMID 36904292, 2023). "Elevated levels of ICAM-1, VCAM-1, CRP and SAA have been associated with coronary artery disease, cancer and psychiatric disorders including schizophrenia." (PMID 33602170, 2021). "Serum VCAM-1 was also reported to be increased among patients with schizophrenia, which could support the neuroinflammatory hypothesis concerning its pathogenesis." (PMID 41225971, 2025). "Previous research has also associated elevated levels of VCAM-1 and ICAM-1 with schizophrenia." (PMID 33602170, 2021). "Previous research demonstrated that T. gondii infection causes neural damage and reactive tissue repair in mice similar to those observed in the brain of schizophrenia patients, and that both T. gondii infections in mice and schizophrenia are associated with elevated levels of CRP and VCAM-1." (PMID 33602170, 2021).
scleroderma (4 papers, 2008 to 2016). Scleroderma is a rare autoimmune connective tissue disorder characterized by abnormal hardening of the skin and, sometimes, other organs. "Suggestive association was also observed between a novel SNP in VCAM1 and overall scleroderma and in limited disease cases, both of which were also associated in the replication dataset." (PMID 25332064, 2014). "VCAM-1 levels have previously been shown to be elevated in early, inflammatory-phase scleroderma and in limited scleroderma." (PMID 25332064, 2014). "VCAM1 has not previously been reported to be associated with scleroderma or SLE." (PMID 25332064, 2014). "Here, we have recapitulated those findings after purifying anti-ICAM-1 antibodies from scleroderma patients, and shown that the purified antibodies bind to the cell surface of HUVEC, and after cross-linking induce an increase in ROS generation and VCAM-1 expression." (PMID 23685129, 2013).
serous ovarian cancer (4 papers, 2016 to 2025). "VCAM1 expression is associated with the tumorigenesis and unfavorable prognosis of high-grade serous ovarian cancer." (PMID 35958614, 2022). "Further, expression of VCAM-1 in high grade serous ovarian cancer was associated with poor prognosis." (PMID 26881177, 2016).
Shock (4 papers, 2015 to 2026). The state in which profound and widespread reduction of effective tissue perfusion leads first to reversible, and then if prolonged, to irreversible cellular injury. "Across baseline severity categories, VCAM-1 showed the clearest gradient (q-value = 0.017), while GzmA concentrations were numerically highest in septic shock (median 165.4 pg/mL)." (PMID 42292430, 2026).
subarachnoid hemorrhage (4 papers, 2017 to 2023). A serious neurological disorder characterized by intracranial hemorrhage into the subarachnoid space. "Brain hemorrhage triggers a local inflammatory response, and consequently, the levels of soluble adhesion molecules (i.e., E-selectin, ICAM-1, VCAM-1, and L-selectin) and inflammatory cytokines are elevated in the CSF of patients after subarachnoid hemorrhage." (PMID 32210955, 2020). "As a sign of local inflammatory response, the levels of E-selectin, VCAM-1, ICAM-1, and L-selectin were found to be elevated in the cerebrospinal fluid (CSF) of patients after subarachnoid hemorrhage." (PMID 32210955, 2020). "In patients with subarachnoid hemorrhage, both ICAM-1 and VCAM-1 were increased in cerebrospinal fluid and serum." (PMID 28753621, 2017).
systemic sclerosis (4 papers, 2004 to 2021). A chronic disorder, possibly autoimmune, marked by excessive production of collagen which results in hardening and thickening of body tissues. "VCAM1 encodes adhesion molecules induced by proinflammatory cytokines, and it has been reported that VCAM1 is increased in systemic sclerosis complicated with PAH." (PMID 33816621, 2021). "Recently, grape seed proanthocyanidins have been demonstrated to reduce the expression of soluble adhesion molecules, ICAM-1, VCAM-1 and E-selectin in the plasma of systemic sclerosis patients." (PMID 15498105, 2004). "Treatment of activin (100 mg/kg/day) in systemic sclerosis patients for 30 days reduced soluble adhesion molecules (i.e., ICAM-1, VCAM-1, E-selectin) and malondialdehyde (MDA) levels in serum." (PMID 34258301, 2021).
triple-negative breast carcinoma (4 papers, 2019 to 2023). An invasive breast carcinoma which is negative for expression of estrogen receptor (ER), progesterone receptor (PR), and human epidermal growth factor receptor 2 (HER2). "VCAM-1 promotes lung-metastases and is associated with clinical early recurrence and poor outcome in triple negative breast cancer (TNBC)." (PMID 31340603, 2019). "In this research, we demonstrate that IL-8 and conditioned medium from triple negative breast cancer cells induce leukocyte adhesion and increase the levels of VCAM-1 at the cell surface." (PMID 37773178, 2023). "TNBC (triple-negative breast cancer) cells exposed to short-term microgravity obtained by parabolic flight maneuvers kept all signs of a more aggressive phenotype, as elevations of ICAM1 and Vascular cell adhesion protein 1 (VCAM1) proteins occurred quickly." (PMID 32013031, 2020).
Acute GVHD (3 papers, 2014 to 2022). "Furthermore, low endocan levels were significantly associated with acute GVHD in the liver and gastrointestinal tract, whereas high VCAM-1 levels were associated with acute GVHD in the skin only." (PMID 25374676, 2014). "Gastrointestinal and liver GVHD were associated with low endocan levels whereas acute GVHD only involving the skin showed increased VCAM-1 levels; a possible explanation for this is organ-dependent differences of the endothelial cell phenotype for the involved organs." (PMID 25374676, 2014). "In mouse models of acute GVHD, allogeneic recipients showed upregulation of VCAM-1, ICAM-1 in the GI tract compared to syngeneic recipients with concomitant increase in T cell infiltration in GVHD target organs of skin, liver and GI tract." (PMID 36505438, 2022).
aortic aneurysm (3 papers, 2013 to 2022). A ruptured aneurysm located in the wall of the proximal portion of the descending aorta proceeding from the arch of the aorta. "Recent studies have shown that the depletion of KIAA1462 decreased the expression of genes such as VCAM1, which is involved in the pathogenesis of ascending aortic aneurysm through increasing the activity of MMP-2 and MMP-9 that promotes aortic aneurysm progression." (PMID 35741789, 2022).
arterial disease (3 papers, 2012 to 2025). "Established arterial disease, Cystatin C and inflammatory markers were strong predictors for both, but s-VCAM-1, a marker of endothelial cell activation, was only associated with CVM." (PMID 22390680, 2012).
autoimmune thyroid disease (3 papers, 2011 to 2025). Inflammatory disease of the thyroid gland due to autoimmune responses leading to lymphocytic infiltration of the gland. "Autoimmune thyroid disease, B cell receptor signaling pathway, natural killer cell mediated cytotoxicity, rig I like receptor signaling pathway, T cell receptor signaling pathway, toll-like receptor signaling pathway were enriched in the high VCAM1 expression group." (PMID 37622107, 2023). "Levels of ICAM-1, vascular cell adhesion molecule-1 (VCAM-1), and tissue inhibitor of metalloproteinases 1 (TIMP-1) were significantly higher in patients with functional abnormality due to the autoimmune thyroid disease than in euthyroid subjects." (PMID 22654557, 2011). "A research investigation revealed that autoimmune-mediated dysthyroidism is linked to elevated levels of vascular cell adhesion molecule 1 (VCAM-1), intercellular adhesion molecule-1 (ICAM-1), and TIMP-1 in peripheral blood when compared to cases of non-autoimmune thyroid disease." (PMID 40095713, 2025).
bone metastasis (3 papers, 2021 to 2023). Transfer of a neoplasm from its primary site to bones. "VCAM‐1 has also been reported to mediate lung and bone metastasis." (PMID 37082943, 2023). "VCAM-1 has been shown to bind osteoclast progenitor cells, inducing differentiation, and this cross-talk represents a critical step in the progression of microscopic bone metastasis to clinically significant bone metastasis." (PMID 34206401, 2021).